CD4 (CD4 molecule)
Diseases named in the same sentence as CD4 in open-access papers (continued):
Sharing a sentence is not in itself a finding about the gene and the disease.
COVID-19 (continued). "Here, we show that in both COVID-19–recovered and –naive individuals, BNT162b2 mRNA vaccination induces robust SARS-CoV-2–specific neutralizing antibodies, ADCC-mediating antibodies, and CD4+ and CD8+ T cells." (PMID 34035118, 2021). "Density UMAP plots revealed the increase of non-Naive cells as one obvious perturbation of peripheral CD4+ T compartments by the COVID-19." (PMID 35095917, 2021). "Virus-specific CD4+ T-cell responses were detected in seven (70%) patients with COVID-19 and virus-specific CD8+ T-cell responses were detected in all 10 patients with COVID-19, further indicating that most individuals can develop T-cell responses to SARS-CoV-2." (PMID 33717166, 2021). "Furthermore, the binding of M protein and TREM-2/CD3ζ/ZAP70 complex was confirmed by IP in COVID-19 lung, which was accumulated with abundant TREM-2+CD4+ T cells." (PMID 34878838, 2021). "However, COVID-19 vaccines can elicit not only neutralizing antibodies, but also SARS-CoV-2-specific CD4+ and CD8+ T-cell responses." (PMID 34023862, 2021). "The percentage of TREM-2+CD4+ T cells was significantly increased in patients with nonsevere (35.56 ± 2.74%) or severe (75.18 ± 3.96%) COVID-19, compared to the low level in healthy donors (6.16 ± 0.49%)." (PMID 34878838, 2021). "Given the persistent T cell activation/exhaustion observed in patients who recovered from COVID-19, we aimed to investigate the CD4+ T cell–dependent response following specific or nonspecific in vitro stimulation using an ex vivo IFN-γ–based ELISpot assay." (PMID 34784300, 2021). "CD4+ T and CD8+ T cells are the centers of antiviral response in COVID-19 patients." (PMID 34234102, 2021). "We validated our findings in the second severely ill patient (“GT_2”) with COVID-19 for which we stimulated or did not stimulate PB CD4 and CD8 T cells with SARS-CoV-2 spike protein–peptide mix." (PMID 34312385, 2021). "The correlation coefficients for TNF-α and IL-2, and TNF-α and IFN-γ were higher in the COVID-19 group than that in the cancer group, while the correlation coefficients between CD3+CD4+ T cells and CD19+ B cells were higher in the cancer group than that in the COVID-19 group." (PMID 34712741, 2021). "Given the absence of significant compositional changes in the baseline naïve, effector, TCM and TEM subsets of CD3+CD4+ and CD3+CD8+ T cells, we then investigated the extent of functional differentiation within the convalescent COVID-19 immunome by stimulating the samples with PMA and ionomycin." (PMID 34113347, 2021). "In the case of inactivated COVID-19 vaccine, Th1 and Th2 T cell subsets were not defined although cellular immune responses in vaccinated individuals exhibited antigen-specific CD4+ and CD8+ T cells." (PMID 34949742, 2021). "We next determined the activation status of CD4+ and CD8+ T cells and observed that patients with moderate and severe COVID-19 show increased accumulation of activated HLA-DR+CD38+CD8+ T cells, which distinguished these cohorts from healthy controls and convalescent individuals." (PMID 34745145, 2021). "Therefore, CD4+ and CD8+T lymphocytes can be considered as early warning signals and prognostic indicators to judge the severity of COVID-19 patients." (PMID 34490135, 2021). "Reduced numbers of CD4+ and CD8+ T cells in COVID-19 patients may be due to failed activation/anergy, or hyperactivation, followed by apoptosis, each of which could contribute to severe COVID-19." (PMID 35593707, 2021). "We stimulated PBMC from six acute COVID-19 patients with the ten most frequently detected peptides, in order to investigate the frequency and functionality of the ex vivo SARS-CoV-2-specific CD4+ T cell response." (PMID 34529740, 2021). "Moreover, a recent study reported that the proportion of Tregs (defined by CD3+ CD4+ CD25+ FoxP3+) and the levels of FoxP3 expression by Tregs were increased in COVID-19 patients, and that was correlated with poor outcome." (PMID 33907514, 2021).
COVID-19 (continued). "In addition, the CD4+ and CD8+ T cells from critically ill COVID-19 patients highly express inhibitory receptor such as T-cell immunoglobulin mucin-3 (Tim-3) and Programmed cell death protein 1 (PD-1)." (PMID 33632295, 2021). "In addition to lymphopenia, other markers involving immune aging have been demonstrated in severe and extremely severe COVID-19 patients including decreased CD28 expression and increased CD45RO (memory phenotype) expression on CD4+ and CD8+ T cells." (PMID 33923792, 2021). "We studied the expression of PD-1 on CD4 T cells and found that there was an increase in all non-naïve CD4 T cells from patients, which was statistically significant in the effector-memory subset from moderate and severe COVID-19 patients." (PMID 33777054, 2021). "A coordinated and regulated response involving all branches of adaptive immunity (CD4+, CD8+ and antibody responses) is likely required to reduce COVID-19 severity, with the cellular response being key for both initiating the adaptive response and for controlling the acute infection." (PMID 34349756, 2021). "Further immunological analysis revealed that male patients had a lower percentage of CD4+ T cells and CD19+ B cells than female patients during the infection and recovery of COVID-19, and the response of protective antibodies was slower in male patients than in female patients." (PMID 34225644, 2021). "We found the decrease of CD4+T cell level, not CD8+T cell level, was an independent risk for in-hospital death in COVID-19 patients." (PMID 33435865, 2021). "DC3 or classical monocytes isolated from COVID-19 patients and healthy controls were cocultured with CellTrace Violet (CTV)-labeled autologous naïve CD4+ T cells (isolated from the same individuals) in the presence of suboptimal TCR stimulation by anti-CD3 antibody." (PMID 34614036, 2021). "Thus, we present transcriptional shifts from acute disease to resolution after virus clearance in antigen reactive CD4 and CD8 T cells during the course of COVID-19." (PMID 34312385, 2021). "In COVID-19, T2DM or hyperglycaemia affected the numbers of immune cells, including CD4+, CD8+ T cells, and NK cells, and reduced Th1/Th2 cytokine ratios, which might aggravate the severity of COVID-19." (PMID 33776910, 2021). "Besides, mounting studies demonstrate that elevated number of activate T cells (CD4 and CD8) showing the tendency toward the exhausted phenotype, is insistent in COVID-19." (PMID 33757410, 2021). "Both CD4+ and CD8+ T cell response is imperative for cell-mediated immune response during COVID-19." (PMID 35250966, 2021). "Primarily, we estimated the CXCR5+ Tfh frequencies within CD3+CD4+CD45RA− memory cell subset and found that COVID-19 convalescent patients had elevated Tfh cell count compared with HC, reflecting the expansion of cell type after acute phase of SARS-CoV-2 infection." (PMID 35723393, 2021). "We observed a slightly higher CD4 to CD8 T-cell ratio in the COVID-19 patient group compared to the controls, although it lacked statistical significance (p = 0.55)." (PMID 34441292, 2021). "SARS-CoV-2-specific CD4+ T cell and antibody responses in lung lesions were observed in all COVID-19 cases, whereas CD8+ T cell responses were observed in not all but most patients in a study." (PMID 32897537, 2021). "Moreover, a drastic decline in the levels of CD4+ T cells, CD8+ T cells, B cells, monocytes, eosinophils, and natural killer (NK) cells was observed in COVID-19 patients." (PMID 34159203, 2021). "The cytostatic effect of HU on CD4 and CD8 T cells may decrease the abnormal production of proinflammatory cytokines during COVID-19, reducing the severity of clinical symptoms." (PMID 34638236, 2021). "Similarly, CD38+HLA-DR+cTfh cells, activated CD4+T cells and cytotoxic CD8+T cells were expanded in COVID-19 patients, and increased CD38+HLA-DR+cTfh cells indicated a recent antigen encounter and emigration from the GC of the patients." (PMID 34603308, 2021).
COVID-19 (continued). "However, lower percentages of ICOS-1+CD8+ T, ICOS-1+CD4+ T, and CD38+CD4+ T cells were observed in severe COVID-19 patients." (PMID 33692788, 2021). "Some HIV+ individuals presenting with COVID-19 have been shown to experience elevated inflammatory markers and severe lymphocytopenia despite ART, and preliminary data suggests the skewed CD4:CD8 ratio seen in some patients after immune reconstitution negatively impacts T cell responsiveness." (PMID 36845567, 2021). "Interestingly, patients with severe COVID-19 present an increased proportion of PD-1+CD8+ and PD-1+CD4+ T lymphocytes compared to patients with mild disease." (PMID 34473802, 2021). "Interestingly, we observed stronger reductions in the absolute numbers of early compared to very late differentiated T cells of the CD4+ and CD8+ lineage in mildly versus severely affected COVID-19 patients." (PMID 34867933, 2021). "Thus, a coordinated adaptive immune response composed of both robust NAbs and long-lasting CD4+ and CD8+ T cells is essential for strong protection and will be critical to a successful vaccination strategy for broad protection against COVID-19." (PMID 34603303, 2021). "The WHO, the United States Department of Health and Human Services, the British HIV Association, and health authorities in Australia recommend that PLWHA receive COVID-19 vaccination regardless of their CD4+ T cell counts." (PMID 34543223, 2021). "Although there had already been prior preliminary evidence supporting an important role for both CD4+ and CD8+ T cells in the immunologic memory component in the host response to COVID-19, it is likely that additional related news on these topics will be forthcoming in the coming months." (PMID 34696319, 2021). "Analysis of patients with moderate and severe COVID-19 alone, there was no significant change in the proportion of decreased CD4+T cell level." (PMID 33435865, 2021). "Such retrospective study leads to a understanding that irrespective of HIV status, patients with COVID-19 still have low counts of CD4+ T cells." (PMID 34295314, 2021). "UNAIDS suggested that PLWH should be given priority in COVID-19 vaccinations regardless of CD4 + T lymphocyte count (CD4 count) and HIV viral load (HIV-VL) levels." (PMID 34863210, 2021). "Moreover, we presented the evidence that both the frequency and epitopes of SARS-CoV-2-specific CD4+ T cells were higher than those of CD8+ T cells, which were consistent with recent findings in COVID-19 convalescents." (PMID 34805136, 2021). "A sophisticated and detailed analysis of T cell immunophenotype in COVID-19 patients has revealed the heterogeneity of the immune response to SARS-CoV-2 infection ranging from robust CD8+ and/or CD4+ T cell activation and proliferation to minimal detectable responses compared to healthy donors." (PMID 34595175, 2021). "In patients with severe COVID-19 but not in patients with mild disease, lymphopenia is a common feature, with drastically reduced numbers of CD4+ T cells and CD8+ T cells." (PMID 33936072, 2021). "This includes evidence of SARS-CoV2 antigen-specific CD4+ and CD8+ T cells in acute COVID-19." (PMID 33525459, 2021). "Likewise, the antigenicity of SARS-CoV-2 S is also apparent through the detection of S-specific CD4+ and CD8+ cells in blood specimens obtained from COVID-19 convalescents." (PMID 33672450, 2021). "COVID-19 patients showed a gradual improvement in exercise capacity, a significant decline in SARS-CoV-2 specific IgG and IgM, a mild increase in CD4+ T cells, and diverse changes in several biochemical and haematological biomarkers 6-month after hospital discharge." (PMID 34766857, 2021). "In addition, the CD3+CD4+ and CD3+CD8+ counts are independent predictors of disease severity in the COVID-19 group and the combined COVID-19 and CAP group." (PMID 34150910, 2021). "In conclusion, reduction of CD4+ T and CD8+ T cell counts were observed in COVID-19 patients." (PMID 34149679, 2021).
COVID-19 (continued). "We found that COVID-19 patient-recovered exosomes were capable of stimulating CD4+ T-cell growth, while HD-recovered exosomes were not." (PMID 35111156, 2021). "The results showed that there were significant differences in the levels of IL-2, IL-10, absolute count of lymphocyte subsets (CD3+ T cells, CD3+CD4+ T cells, CD3+CD8+ T cells, and CD19+ B cells), CD16+CD56+ NK cells, and neutrophils between patents with COVID-19 and cancers." (PMID 34712741, 2021). "In contrast, the expression of IL-10, a prototypical regulatory cytokine, was significantly increased in CD4+T cells from nonhospitalized patients after stimulation with M peptides when compared to the mild COVID-19 group (p = 0.035)." (PMID 34021148, 2021). "Thus, CD4+ and CD8+ T cells were both affected by the lymphopenia in COVID-19 ICU patients, and particularly elevated CD8+ TEMRA T-cell numbers in CONV suggest a pronounced T-cell differentiation during SARS-CoV-2 infection." (PMID 34893580, 2021). "We further measured the changes in CD4+ T cell counts and VL before and after vaccination, and the results demonstrated that a COVID-19 vaccine had no negative impact on either CD4+ T cell counts or VL during the study period." (PMID 34960204, 2021). "Durable immunity after recovery from symptomatic COVID-19 was reported in a cohort of 188 COVID-19 cases, mostly with mild disease, with ~95% of subjects presenting with SARS-CoV-2 specific antibodies, memory B cells, CD4+ and CD8+ T cells 6 months after the initial infection." (PMID 34976939, 2021). "In addition, we analyzed the alteration of major immune cell types (CD4+, CD8+ T cells, B cells and NK cells) in 117 cancer patients and showed that lymphocytes were diminished in cancer patients who died from COVID-19." (PMID 33735106, 2021). "This could explain why we detected the binding of M protein with TREM-2 and CD3ζ as well as ZAP70 in the lung tissue of patients with COVID-19, where abundant infiltrating TREM-2+CD4+ T cells were found." (PMID 34878838, 2021). "Meanwhile, the anti-inflammatory subset Th2 and Treg, represented by CCR3+CD3+CD4+ and CCR5+CD25+CD3+CD4+ markers, respectively, both the naïve and memory phenotypes, were upregulated in our COVID-19 cohort relative to HCs, suggesting immunoregulation and counter-inflammatory mechanisms." (PMID 33808906, 2021). "On the contrary, other studies performed on COVID-19 patients showed that the CD4:CD8 ratio was not reduced, whereas a reduction of the total number of both CD4+ and CD8+ lymphocytes in the blood was observed." (PMID 34573988, 2021). "With PBMCs from COVID-19 convalescent donors, the tetramer guided epitope mapping (TGEM) approach was used to identify CD4+ T cell epitopes within Spike (S), Nucleocapsid (N) and Membrane (M) proteins of SARS-CoV-2 utilizing peptides derived from the US-WA1/2020 strain." (PMID 34965282, 2021). "In patients with COVID-19, we found immune cells from myeloid lineage (M1 macrophages, neutrophils, and MAST cells) increased significantly (FDR ≤10%) and lymphoid cells (CD4+ and CD8+ alpha-beta T cells, B cells) decreased significantly (FDR ≤10%) during viral infection." (PMID 33437935, 2021). "When the number of peripheral CD3+CD4+ and CD3+CD8+ T cells in COVID-19 patients continuously increased 6-9 days after baseline, the period of disease exacerbation could be delayed for more than 2 weeks after admission." (PMID 33741750, 2021). "Over 80% of patients with COVID-19 experience lymphopenia and exhibit drastically reduced numbers of various lymphocyte subsets, including CD4+ T, CD8+ T, B, γδ T, and NK cells, especially in the peripheral blood of those with severe COVID-19 during the acute phase (16, 30, –, 34)." (PMID 34488453, 2021). "We observed changes in the composition of pDCs, CD8+ T cells and CD4+ T cells, along with the emergence of plasmablasts in moderate and severe COVID-19 patients, a feature no longer observed in convalescent patients." (PMID 34745145, 2021).
COVID-19 (continued). "Moreover, an increase in CD4+CD127-CD25+Treg cells was found in mild patients, and upregulation of CCR4 in activated CD8+T cells indicated enhanced lung homing in severe COVID-19 patients." (PMID 34603308, 2021). "Besides serum titers, antigen specific CD4+ and CD8+ T cell responses also contribute to the COVID-19 vaccine efficacy." (PMID 34439346, 2021). "This study suggests that, in addition to preexisting cross-reactive memory CD4+ T cells reported previously, dissimilar SARS-CoV-2 epitope–specific CD8+ T cell responses could also contribute to divergent COVID-19 clinical outcomes." (PMID 34210785, 2021). "We also identified a few consensus CDR3 sequences shared in CD8+ T but not CD4+ T cells of convalescent COVID-19 patients." (PMID 35011632, 2021). "Further, NAbs alone did not predict disease severity in COVID-19 patients, whereas both the presence of SARS-CoV-2 S-specific CD4+ and CD8+ T cells were significantly associated with less severe disease." (PMID 34603303, 2021). "However, it has been reported that CD4+ T cells and CD8+ T cells decreased more in the severe cases of COVID-19 than in the mild cases." (PMID 33937149, 2021). "If superimposed on low CD4 counts in patients with advanced HIV disease, the lymphopenia of COVID-19 could delay the clearance of SARS-CoV-2 and promote disease progression." (PMID 33952300, 2021). "We next profiled CD4+ and CD8+ T cells in COVID-19 patients and healthy donors." (PMID 33361110, 2021). "A marked reduction in the absolute number of total lymphocytes and T cell subsets (CD4+, CD8+ T, Th1, Th17 and Treg) was recorded in severe COVID-19 patients compared to mild or moderate subjects, while the number of granulocytes was significantly increased in severe patients." (PMID 34925369, 2021). "The fact that T cell populations, including CD4+ and CD8 + T cells, are reduced in COVID-19 patients suggests impaired or dysregulated cellular immunity in these patients and may be explained by several mechanisms." (PMID 34251989, 2021). "Indeed, CD4+ and CD8+ effector T cells, specific for SARS-CoV-2, are found in the convalescent individuals after mild COVID-19." (PMID 33608656, 2021). "Moreover, both CD4+ and CD8+ T cells from COVID-19 patients overexpressed CD69 and TIM-3 compared with healthy controls, which is compatible with a hyperactivated pan T-cell exhaustion profile." (PMID 33060840, 2021). "Taken together, and compared with non-severe COVID-19, there is mounting evidence that severe COVID-19 disease is associated with a reduced frequency of CD3+ T cells affecting both CD4+ and CD8+ T cells in the peripheral circulation." (PMID 35965490, 2021). "We first identified CD4+ and CD8+ T cell clones with certain clonal expansion after infection, and then observed the preferential recombination usage of V(D) J gene segments in CD4+ and CD8+ T cells of COVID-19 patients with different convalescent stages." (PMID 35011632, 2021). "The observed cross-reactive effects of CD4+ and CD8+ T cells may be of importance in swift and effective viral clearance of SARS-CoV-2, reducing the severity of symptoms in COVID-19 patients pre-vaccinated with BCG." (PMID 34421902, 2021). "In the obesity subgroup, compared to the nonsevere patients, peripheral levels of CD4+ cells were decreased in severe COVID-19 patients." (PMID 33746594, 2021). "Interestingly, comparing the frequency of double-positive (IFNγ+ TNF+) CD4+ and CD8+ T cells within individuals, these were higher in both COVID-19 patients and close contacts than in healthy controls." (PMID 33741972, 2021). "In COVID-19 patients with ARDS, peripheral blood CD8:CD4 ratio was decreased compared to healthy controls, which may be a result of CD8+ T cell migrating to the respiratory tract." (PMID 34766001, 2021).